C14orf132 (chromosome 14 open reading frame 132)
Synonyms: C14orf88
Tractability: Antibody: UniProt predicts a signal peptide or a membrane-spanning region.
Gene: Protein-coding gene on chromosome 14 (96,039,362 to 96,093,971, forward strand). Ensembl gene ENSG00000227051.
Subcellular location: Membrane
Gene Ontology:
Cellular component: membrane
Genetic constraint (gnomAD): Loss-of-function variants: 6 observed, 4.74 expected, observed/expected ratio (o/e) 1.26, 90% interval 0.66 to 1.89. That is too few expected variants to judge how well the gene tolerates losing a copy. Missense variants: 125 observed, 117.87 expected, observed/expected ratio (o/e) 1.06, 90% interval 0.92 to 1.23. Synonymous variants: 51 observed, 50.5 expected, observed/expected ratio (o/e) 1.01, 90% interval 0.81 to 1.27.
Homologues: Orthologues: chimpanzee C14H14orf132 (100% identical), rabbit C14orf132 (98% identical), guinea pig C14orf132 (96% identical), pig C14orf132 (96% identical), macaque C14orf132 (93% identical), tropical clawed frog c8h14orf132 (90% identical), mouse D430019H16Rik (89% identical), rat D430019H16Rik (89% identical), zebrafish C17H14orf132 (75% identical).
Diseases named in the same sentence as C14orf132 in open-access papers:
C14orf132 is named in the same sentence as 9 diseases in open-access papers, as found by Europe PMC text mining. Sharing a sentence is not in itself a finding about the gene and the disease. The quoted sentences say what the papers report.
non-small cell lung carcinoma (2 papers, 2016 to 2022). A group of at least three distinct histological types of lung cancer, including non-small cell squamous cell carcinoma, adenocarcinoma, and large cell carcinoma. "Previously it has been reported that C14orf132 is one of the most significantly downregulated lincRNA in hepatocellular carcinoma cell line and non-small-cell lung carcinoma." (PMID 27660052, 2016). "The present study estimated the usefulness of 14 lncRNAs (HAGLR, ADAMTS9-AS2, LINC00261, MCM3AP-AS1, TP53TG1, C14orf132, LINC00968, LINC00312, TP73-AS1, LOC344887, LINC00673, SOX2-OT, AFAP1-AS1, LOC730101) for early detection of non-small-cell lung cancer (NSCLC)." (PMID 35053601, 2022).
bladder urothelial carcinoma (1 paper, 2022). "High expressions of STON1 and C14orf132 were correlated with worse prognosis in bladder urothelial carcinoma and CRC, respectively." (PMID 35681225, 2022).
developmental delay (1 paper, 2016). "C14orf132 gene is a novel long non-coding RNA (lincRNA) with unknown function, which might be associated with the pre- and early postnatal developmental delay through the altered gene expression." (PMID 27660052, 2016). "Namely, according to the NCBI ClinVar database, which provides a comprehensive information about the known clinical conditions for every genomic region, the locus harbouring C14orf132 gene has been claimed to be related to the phenotype of “global developmental delay”." (PMID 27660052, 2016). "Thus, the proof that the C14orf132 gene is related to the phenotype with “global developmental delay” still should be confirmed in future studies." (PMID 27660052, 2016).
endometriosis (1 paper, 2017). The growth of functional endometrial tissue in anatomic sites outside the uterine body. "Of these eight loci, three were associated with all endometriosis (LAMC3, CAPN14 and DEFA1), and six with Stage B disease (NAALADL2, NR2C1, C14orf132, FOXP2, CDH20 and LAMC3)." (PMID 28333195, 2017).
tumor (1 paper, 2022). "We showed that C14orf132 and LINC00968 were downregulated in tumors (NSCLC, LUAD and LUSC) in comparison to matched normal lung tissue and not statistically significant in LUAD tumor vs. LUSC tumor." (PMID 35053601, 2022).
C14orf132 also shares sentences with these, for which no sentence is quoted: cancer (2 papers); colon cancer (1); hepatocellular carcinoma (1); prostate carcinoma (1).